EZH2 (enhancer of zeste 2 polycomb repressive complex 2 subunit)
Diseases named in the same sentence as EZH2 in open-access papers (continued):
Sharing a sentence is not in itself a finding about the gene and the disease.
cancer (continued). "Among the molecular mechanisms responsible for such actions EZH2 has been described to be involved in regulating both cancer cell immunogenicity, through the silencing of immuno-attractant cytokines and antigen presentation-related genes, and T cell anti-tumor responses." (PMID 34968293, 2020). "The last 25 years’ comprehensive study on EZH2 demonstrates a splendid landscape that a histone methyltransferase is able to participate in numerous biological processes, especially in oncogenesis and cancer distant metastasis." (PMID 33308321, 2020). "EZH2 upregulation results in cancer development and poor prognosis of cancer patients." (PMID 33308321, 2020). "We also discussed the therapeutic potential of targeting EZH2 modifications for cancer therapy." (PMID 33308321, 2020). "HMTs such as EZH2 and G9a have be found overexpressed in different types of cancer." (PMID 33194754, 2020). "Meanwhile, EZH2 expression in regulatory T cells (Tregs), helper T (Th) cells, and natural killer (NK) cells could suppress anti-cancer immunity." (PMID 32723346, 2020). "A study suggested the possibility that combined immunohistochemical expression of EZH2, H3K4me2, and H3K27me3 might identify cancer cells with potential stem cell properties; another relevant data that many epigenetic changes are pharmacologically reversible." (PMID 32850962, 2020). "However, how these crosstalks of EZH2-PTMs are precisely regulated in cancer progression has yet to be elucidated." (PMID 33308321, 2020). "Thus, metformin can serve as an anti-cancer drug for EZH2-overexpressing solid tumors in the future." (PMID 33308321, 2020). "An in vivo experiment proves the important role of EZH2 in cancer cells metastasis." (PMID 32723346, 2020). "The role of EZH2 in different cancers is complex and gene-dependent." (PMID 32483123, 2020). "The effect of DZNep on cancer cells is relatively specific for targeting EZH2." (PMID 32436117, 2020). "Hypermethylation might be driven by the methyl-CpG binding proteins, such as DNA methyltransferases and enhancer of zester homolog 2 (EZH2), which are known to be upregulated in TILs as well as in cancer cells themselves." (PMID 32194559, 2020). "Indeed, many of these microbes’ abundance correlated with the increased activity of cancer-associated pathways, including the AKT, ERK, EZH2, and ATF2 pathways." (PMID 32575865, 2020). "Aside from these small molecules, certain inhibitors may also be used as potential anti-cancer strategies to inhibit EZH2 HMTase activity or protein stability." (PMID 33308321, 2020). "Several of the epigenetic enzymes targeted by these drugs, such as DNA methyltransferases (DNMTs), histone deacetylases (HDACs), the histone demethylase (HDM) LSD1/KDM1A and the histone methyltransferases (HMTs) EZH2 and G9A, play a role in the transcriptional repression of TEs in cancer cells." (PMID 34968293, 2020). "It has been long recognized that EZH2 plays a crucial role in regulating cancer cell proliferation." (PMID 33121524, 2020). "TET2 and EZH2 play important roles in the epigenetic regulation in many cancers." (PMID 32066746, 2020). "EZH2 frequently functions as a specific H3K27 methyltransferase to intrinsically catalyze histone H3K27me3, which is a vital step of the fundamental biological processes of human cancers, and EZH2 has been largely acknowledged as a promoter of cancer development." (PMID 33292225, 2020). "Our findings support the thought that EZH2 is not only a target for various types of cancer but may also serve as novel target for auto-immune diseases." (PMID 33574814, 2020). "EZH2, as a transcriptional inhibitor, participates in cancer development." (PMID 33299646, 2020). "Similarly, 56.4% of cancer tissues were positive for H3K27me3, the enzyme end-product of EZH2, compared to 7.3% of normal gastric mucosa samples." (PMID 33050946, 2020).
cancer (continued). "Further studies in this aspect are still needed, and an overview of EZH2 PTMs in cancer development might help researchers fill in this research gap." (PMID 33308321, 2020). "Other studies have also shown that miR-138-5p could inhibit the promoter of the epigenetic regulator EZH2 in cancers and nervous system diseases 43-45." (PMID 32292524, 2020). "EZH2 is involved in treatment resistance in multiple cancers." (PMID 33056982, 2020). "The enhancer of zeste homolog 2 (EZH2) is a histone methyltransferase and induces the trimethylation of histone H3 lysine 27 (H3K27me3) in the promoter of many key genes; EZH2 acts as a transcriptional repressor and is an epigenetic regulator for several cancers." (PMID 32508971, 2020). "EZH2 has been studied mainly in relation to developmental biology and cancer research." (PMID 33574814, 2020). "As a novel and potential target for cancer therapy, EZH2 has become a hotspot of research." (PMID 32723346, 2020). "Previous data revealed that miR-26a and miR-101 could downregulate EZH2 which decreases self-renewal capacity and induces apoptosis in cancer cells." (PMID 32512882, 2020). "In conclusion, understanding the regulation of EZH2-PTMs and their crosstalks in cancer progression and demonstrating their molecular mechanisms in depth will open a promising way for the development of novel cancer therapeutic strategies." (PMID 33308321, 2020). "DZNep - an indirect EZH2 inhibitor - is known to be efficacious against many different types of cancer and, hence, may make its way into clinical trials." (PMID 32408898, 2020). "This difference in ablation of EZH2 vs. EZH2 inhibition may well explain why in some cancer models, EZH2 modulation can negatively or positively impact the antitumoral immune response." (PMID 33117406, 2020). "More and more functions and roles of EZH2 in multiple kinds of cancer have been revealed." (PMID 32723346, 2020). "Moreover, the transcription factor MYC has been suggested as a positive regulator of EZH2 by different mechanisms in several types of cancers." (PMID 33014831, 2020). "In particular, the 1-benzyl-3,5-bis((E)-3-bromobenzylidene)piperidin-4-one 3 behaved as dual p300/EZH2 inhibitor and displayed cancer-selective growth arrest and cell death in hematological malignancies as well as solid tumors, in in vitro, ex vivo, and in vivo models." (PMID 32650558, 2020). "Besides, matrix-metalloproteinases (MMPs), which were closely related to the cancer cells invasion and metastasis, were downregulated by EZH2 knockdown." (PMID 32723346, 2020). "In fact, EZH2 inhibitors have even been identified as cancer prevention drugs." (PMID 32747629, 2020). "EZH2 functions to inhibit tumor suppressor genes in many cancer tissues including GBM." (PMID 33473259, 2020). "Indeed, histone methyltransferase EZH2 (part of the PRC2 complex) is essential for survival and growth of SMARCA4-deficient cancer cells." (PMID 31996670, 2020). "EZH2 overexpression has been described in various human cancers including NSCLC." (PMID 33276757, 2020). "EZH2 expression in both cancer cells and immune cells have effects on cancer immunity." (PMID 32723346, 2020). "Finally, as a promising target, we proposed a novel strategy through a combination of EZH2 inhibitors with metabolic regulators for future cancer therapy." (PMID 32448308, 2020). "Ezh2 is directly targeted by let-7 microRNAs in primary fibroblasts and cancer cells." (PMID 32479258, 2020). "Interestingly, EZH2 is a downstream target of E2F, has E2F binding sites in its promoter region and is required for E2F driven cell proliferation in both normal and cancer cells." (PMID 33246425, 2020). "Moreover, growing evidences demonstrate that downregulation of EZH2 was essential for inducing autophagy and apoptosis in many types of cancer cells." (PMID 33304896, 2020).
cancer (continued). "Indeed, acute viral models have shown that loss of Ezh2 results in increased expression of memory-associated transcripts such as Tcf7, which is associated with stem-like CD8+ T cells in cancer." (PMID 33117406, 2020). "Such conversions may be dependent on a specific molecular context in the concerned cancers, for instance regarding EZH2 this could be either a concomitant overexpression of ATM or changing features in the interplay with Rev729,44." (PMID 33230143, 2020). "Collectively, our findings suggest thatcombined treatment with a USP7 inhibitor and an EZH2 inhibitor may be a rationalstrategy for the treatment of EZH2-dependent cancers." (PMID 32453339, 2020). "Therefore, targeting EZH2 for cancer therapy is a hot research topic now and different types of EZH2 inhibitors have been developed." (PMID 32723346, 2020). "It is known that EZH2 also promotes lipid synthesis in cancer cells." (PMID 32448308, 2020). "Thus, EZH2 is a relevant target in cancer therapies attempting to improve T cell recruitment into the TME." (PMID 33117406, 2020). "Previous studies suggest that EZH2 has an important role in cancer development and progression." (PMID 33168810, 2020). "Additionally, EZH2 overexpression has been shown to promote migration, cell proliferation and invasion in different in vitro cancer models." (PMID 33003334, 2020). "Furthermore, in high-grade serous cancers (HGSOC) another mechanism involving EZH2 was recently reported in CARM1 overexpressing cancers." (PMID 33230143, 2020). "Therefore, further investigations are still needed before the clinical application of anti-EZH2 PTMs in cancer therapy." (PMID 33308321, 2020). "Additionally, EZH2 activity can be regulated by the lncRNA HOX transcript antisense RNA (HOTAIR), which is associated with poor survival in diverse cancers." (PMID 33344253, 2020). "Data from TCGA datasets showed that EZH2 was highly expressed in various cancers, including HCC." (PMID 33121524, 2020). "To further understand how DEGs were regulated, we analysed transcription factor (TF) binding using Enrichr and observed that DEGs were enriched for targets of TFs associated with self-renewal and cancer stem cell function (SUZ12, SOX2, REST, EZH2, SMAD4 and NANOG)." (PMID 31014368, 2019). "More recently, EZH2 inhibition was found to facilitate natural killer (NK) cell-mediated cancer cell eradication through re-expression of NK cell ligands in HCC cells, suggesting the use of EZH2 inhibitors in rendering HCC cells more susceptible to NK-mediated cytotoxicity." (PMID 31056726, 2019). "Thus, in cancer cells with MLL3 or BAP1 mutations, reduction of H3K27me3 via EZH2 inhibitors can restore the balance of H3K27me3 at enhancers where UTX is not properly recruited." (PMID 31221981, 2019). "GSK126, an EZH2 inhibitor, significantly inhibited cell proliferation of some types of cancers." (PMID 31092221, 2019). "Furthermore, the role of Ezh2 in the homeostatic regulation of cancer stem cells has also been recognized." (PMID 30621625, 2019). "More and more evidences show that EZH2 is involved in diverse fundamental cell processes, including cell proliferation and differentiation, cell cycle regulation and fate decision, tumorigenesis, cancer stem cell maintenance, and drug resistance." (PMID 31718595, 2019). "Firstly, given that EZH2 inhibitors have been developed for cancer therapy, our in vitro data suggest that combining external beam RT and EZH2 inhibitors to treat PCa patients may not result in clinical benefit in terms of radiosensitization per se." (PMID 31104332, 2019). "Therefore, it is possible, like in other types of cancer that c-Myc and EZH2 overexpression cooperate in the pathogenesis of MDS, mainly during evolution to AML." (PMID 31886200, 2019).
cancer (continued). "It seems that EZH2 knockdown exhibits stronger neuron differentiation effect in cancer cell lines." (PMID 31130994, 2019). "Similarly, it was observed that EZH2 repressed a panel of microRNAs and promoted cancer cell growth and invasiveness." (PMID 31171769, 2019). "In addition, ANRIL, frequently overexpressed and tumorigenic in a panel of cancers, forms a ternary complex with EZH2 and P65, and epigenetically marks and represses P21/CDKN1A transcription in adult T cell leukemia." (PMID 31752930, 2019). "Interestingly, there is a stronger agreement concerning the significance of the EZH2-dependent H3K27me3 code for cancer prognosis." (PMID 31317325, 2019). "Thus, by redistributing EZH2 on chromatin, cancer cells remove physiological breaks that normally restrain cellular plasticity and enhance their malignant phenotypes." (PMID 31468686, 2019). "De‐repression of HOX genes, major EZH2 targets in normal brain cells, is thus a likely mechanism through which the physiological function of EZH2—maintenance of cell identity—is compromised in cancer." (PMID 31468686, 2019). "Previous reports have shown that EZH2 is highly expressed in cancer compared with normal tissue." (PMID 30926792, 2019). "We therefore focused on EMX2, which becomes an EZH2 target specifically in cancer cells." (PMID 31468686, 2019). "EZH2 is highly expressed in numerous cancers, including RCC." (PMID 30755832, 2019). "Blockage of Ezh2 activity by either inhibitor or miRNA mimics could overcome Doc resistance by suppressing Doc-induced cancer stem cells populations." (PMID 30621625, 2019). "Thus, our findings uncover a molecular module that links the role of FOXO1 to the action of EZH2 inhibitor in cancer." (PMID 31410199, 2019). "Moreover, overexpression of miR29b strongly decreased cell proliferation, migration, and invasion, suggesting that EZH2 negatively controlled autophagy and inhibited its pro-cancer effects." (PMID 31861179, 2019). "EZH2, a component of the polycomb repressive complex 2, is involved in stable transcriptional repression during embryogenesis and under pathological conditions such as cancer." (PMID 31317325, 2019). "EZH2 is highly expressed and functions as an oncogene in numerous types of cancer." (PMID 30626446, 2019). "In terms of mechanism, we found that SNHG6 could act as a molecular sponge of miR-26a, miR-26b, and miR-214 in the cytoplasm and exert its cancer-promoting effects by regulating EZH2, a common target of these microRNAs." (PMID 30626446, 2019). "Ezh2 has been 5documented as an oncogene in various cancers." (PMID 30621625, 2019). "EZH2 is found to be overexpressed and exert oncogenic activity in multiple cancer types." (PMID 31186379, 2019). "Overexpressed EZH2 mediated repression of these genes reveals its multifaceted role in cancer." (PMID 30760814, 2019). "The EZH2 aberrant expression in cancer cells may result from different mechanisms involved in poor prognosis with evolution of disease." (PMID 31886200, 2019). "Key roles of EZH2 in cancer progression rationalize the investigation of its existing targets." (PMID 30760814, 2019). "We sought to determine whether EZH2 regulation of FOXO1 expression plays any role in the anti-cancer effect of EZH2 inhibitor." (PMID 31410199, 2019). "Additionally, G9a, EZH2, and LSD1, which are key epigenetic repressors frequently overexpressed in cancer cells and associated with cancer-related phenotypes, have been recently suggested as new potential targets to restore autophagy cell death." (PMID 31861179, 2019). "Thus, EZH2 is a potent target for cancer therapy and EZH2 inhibitors have been under pre-clinical and clinical investigations." (PMID 31886200, 2019). "Together, these data suggest that activation of the AKT signaling might play an important role in cancer resistance to EZH2 inhibitors." (PMID 31410199, 2019). "Enhancer of zeste homolog 2 (EZH2) is widely involved in many cancers." (PMID 30733705, 2019).
cancer (continued). "Thus, by redistributing EZH2 across the genome, cancer cells subvert developmental transcriptional programmes that specify normal cell identity and remove physiological breaks that restrain cell proliferation." (PMID 31468686, 2019). "LincRNA/EZH2-based targeting therapy may represent an alternative and complementary strategy in lincRNA/EZH2-dependent human cancers." (PMID 30764859, 2019). "Mounting evidence suggests that lncRNAs could regulate cancer phenotypes via interaction with EZH2 and LSD1." (PMID 31186379, 2019). "Importantly, introduction of Ezh2 into LNCaP and CWR22Rv1 was sufficient to bestow cells with the properties of cancer stem cells, which was consistent with previous publications." (PMID 30621625, 2019). "There is a signalling link between CDK1 and EZH2, with a relevant role in cancer cell invasion." (PMID 31591432, 2019). "The highly context-dependent role of the PRC2 complex in cancer illustrated by these studies emphasizes the need to consider systemic and long-term treatment with EZH2 inhibitors with caution and calls for a more precise understanding of the downstream mechanisms underlying PRC2 function in cancer." (PMID 31015297, 2019). "Overexpression of EZH2 has been found in different cancer types." (PMID 31886200, 2019). "Further study we found that Ezh2 could increase the population of cancer stem cells by regulating Nanog, Sox2, CD44." (PMID 30621625, 2019). "For example, Cdkn2a serves as a cell cycle regulator downstream of Ezh2 in a variety of cancers." (PMID 31259687, 2019). "Interestingly, our previously studies demonstrated that a major part of cancer promoting genes, including the genes for EZH2, LSD1, HDAC1/3, DNMT1, SMAD2/4, or β-catenin, are specifically expressed in embryonic neural cells." (PMID 31130994, 2019). "Moreover, EZH2 inhibition blocks the progression of SMARCB1 mutant cancers in vivo, which has motivated the establishment of ongoing clinical trials with EZH2 inhibitors in RTs." (PMID 31123059, 2019). "Remarkable role of EZH2 in cancer highlights the importance of identifying its targets." (PMID 30760814, 2019). "EZH2 is a multifunctional molecule that has an oncogenic function in various cancers." (PMID 31497532, 2019). "Furthermore, recent evidence suggests that co-downregulation of multiple such epigenetic pathways, including BMI1 and EZH2, is needed to obtain a significant biological effect in cancer cells." (PMID 30683859, 2019). "A H3K27me3-independent EZH2-mediated transcriptional activation was previously reported in cancers." (PMID 30755708, 2019). "In cancer cells with mutations in the SWItch/Sucrose non-Fermentable (SWI/SNF) complex, this non-canonical function of EZH2 is necessary, although this necessity can be bypassed by introduction of a Ras mutation in various cancer cells." (PMID 31277415, 2019). "It was still unclear whether and how EZH2 overexpression in cancer cells contributes to angiogenesis." (PMID 30287808, 2018). "Targeting functional activation (H3K27me3) of EZH2 could be a wonderful strategy to mitigate drug resistance and cancer metastasis." (PMID 29460395, 2018). "Prolonged exposure to EZH2 inhibitors can confer resistance to the drug in many cancer cell lines." (PMID 29710783, 2018). "Collectively, all these findings strongly suggest that posttranslational regulation of EZH2 might be of particular importance with regards to its diverse and complex implication in cancer development and growth." (PMID 29556394, 2018). "Mutations in EZH2 result in a dependency on its enzymatic activity for proliferation that could make EPZ005687 a treatment for cancers in which EZH2 is genetically altered." (PMID 30466474, 2018). "All these findings provide better understanding of EZH2 regulation at the transcriptional level and allow therapeutic combinations of pathway targeting agents and EZH2 inhibitors to achieve maximum therapeutic benefit in cancers." (PMID 29556394, 2018).